IFNG (interferon gamma)
Diseases named in the same sentence as IFNG in open-access papers (continued):
Sharing a sentence is not in itself a finding about the gene and the disease.
tuberculosis (continued). "A recent break through in TB diagnosis is the introduction of interferon gamma release assay (IGRA) in which the production of interferon gamma (IFN-γ) in response to Mycobacterium tuberculosis specific antigens is measured." (PMID 20140219, 2010). "In TB endemic regions, IFNγ can be modulated by natural exposure to M. tuberculosis or non-tuberculous mycobacteria as well as BCG vaccination." (PMID 19340290, 2009). "M. tuberculosis-induced IFNγ levels were significantly lower in TB patients (p = 0.042, Kruskal Wallis analysis)." (PMID 20041183, 2009). "Increased M. tuberculosis- and M. bovis BCG - induced CCL2 and IL10 and decreased IFNγ responses in TB patients." (PMID 20041183, 2009). "These include the T-SPOT-TB and the QuantiFERON®-TB Gold tests.These tests measure interferon gamma released in response to T-cell stimulation by specific Mycobacterium tuberculosis antigens." (PMID 19561914, 2009). "Unlike Th1-mediated cytokines such as interferon-gamma that promote the killing of infected cells, regulatory cytokines including interleukin-10 have been implicated in the suppression of in vitro antigen-specific cellular immune responses in tuberculosis." (PMID 17726533, 2007). "Interferon-gamma (IFN-γ) ELISPOT assays incorporating Mycobacterium tuberculosis-specific antigens are useful in the diagnosis of tuberculosis (TB) or latent infection." (PMID 17725839, 2007). "Interferon-gamma release assays (IGRA) are widely used for detecting infection, but the role of their quantitative values in differentiating active tuberculosis from latent tuberculosis infection has been uncertain." (PMID 41665373, 2026). "Interferon-gamma release assays (IGRAs), such as the QuantiFERON®-TB Gold Plus (QFT), are widely used for tuberculosis (TB) screening in children." (PMID 40821343, 2025). "In tuberculosis, classical tools, such as sputum microscopy, chest radiography, and MRI, remain important, while more advanced tests, like GeneXpert MTB/RIF, and interferon-gamma release assays (e.g., Quantiferon TB Gold) provide higher specificity." (PMID 41149052, 2025). "The key cytokines and chemokines that play a role in the comorbidity of COPD and tuberculosis are interleukins 1β, 6, and 8 (IL-1β, IL-6, IL-8), TNF-α, and interferon gamma (IFN-γ)." (PMID 40141021, 2025). "Our patient exemplified this variant: all TB tests (interferon-gamma release assay and tissue PCR) were negative, in line with recent studies where most EI cases in low-TB settings showed no M. tuberculosis DNA." (PMID 41267735, 2025). "The interferon-gamma release test has high sensitivity and specificity in diagnosing Mycobacterium tuberculosis, avoiding unnecessary trauma to patients and providing a valuable reference for early diagnosis of extrapulmonary TB." (PMID 39247000, 2024). "Immunological TB assays, such as interferon gamma release assays (IGRA), tuberculin skin tests (TST) or tuberculosis antigen-based skin tests (TBST), identify infection indirectly by measuring host responses to M.tb antigens, and have been found to have similar sensitivity." (PMID 38768253, 2024). "In the event of close contact with a person with active tuberculosis, the tuberculin skin test (TST) and interferon-gamma release assay (IGRA) should be performed, as should a chest X-ray (LE IIIb; GR D; LA 100%)." (PMID 37439850, 2023). "Splenocytes from M. tuberculosis-infected mice from the BCG prime TB/FLU-04L boost group produced significantly higher amounts of IFNγ and IL17 after in vitro stimulation with BCG (105 CFU) in comparison with spleen cells derived from control mice as well as BCG-only vaccinated non-boosted mice." (PMID 37108602, 2023). "The infection of tuberculosis was diagnosed by immunological methods: Mantoux tubulin skin test (TST) and interferon gamma release assay (IGRA)." (PMID 37901241, 2023). "TB, tuberculosis; CXR, chest radiograph; TST, tuberculin skin test; IGRA, interferon-gamma release assay." (PMID 37195976, 2023).
tuberculosis (continued). "The interferon-gamma release assay (IGRA) of tuberculosis (TB) in blood was positive." (PMID 37936073, 2023). "For instance, T cells in lung tissue in IL-32γ-transgenic mice infected with Mtb expressed higher levels of interferon gamma (IFN-γ) and TNF-α, and IL-32 was correlated with the balance of TH1/TH17 cytokines in the peripheral blood of tuberculosis patients." (PMID 35880892, 2022). "We compared two assays for the diagnosis of LTBI: transcript signatures and interferon gamma release assay (IGRA), among household contacts (HHCs) in a high tuberculosis-burden population." (PMID 35416716, 2022). "Other factors in the pleural fluid, such as interferon-gamma and carcinoembryonic antigen (CEA), are also valuable biomarkers for diagnosing tuberculosis and malignancy, respectively; however, most patients in our study did not have those levels measured." (PMID 36131272, 2022). "Low expression of IFNγ may imply impaired macrophage activation leading to active TB disease as IFNγ is central in activating macrophage response to Mycobacterium tuberculosis complex (MTBC)." (PMID 35025927, 2022). "Considering functional data, HLA-DR-expressing NK cell subset may be an important source of IFNγ during the antibacterial immune response, due to its expansion in the peripheral blood of TB patients and in response to M. tuberculosis sonicate in vitro." (PMID 34012446, 2021). "IFNγ and IL10 have been suggested as biomarkers for parasitic and other infections, such as tuberculosis." (PMID 33767693, 2021). "Both TST and interferon-gamma release assays (IGRA) perform reasonably well in high-TB burden settings and correlate well with proxy measures of exposure to mycobacterium tuberculosis among the HIV-infected persons and contacts exposed to smear positive index cases." (PMID 32614873, 2020). "In South Africa, dogs have been shown to become infected with M. tuberculosis, as diagnosed using human interferon gamma release assays (IGRA), when exposed to high risk humans, that is, those with active TB disease (Parsons, Warren, Ottenhoff, Gey van Pittius, & van Helden, 2012)." (PMID 30058193, 2018). "For the diagnosis of tuberculosis, it should be borne in mind that both the tuberculin skin test (TST) and interferon gamma release assay (IGRA) have highly variable sensitivity, even in active cases of tuberculosis." (PMID 28120106, 2017). "Elsewhere, differences in IFNγ+TNFα+IL-2+, TNFα-single positive CD4+ T cells or a general increase in multi-cytokine producing T cells expression were observed between tuberculosis patients and contacts." (PMID 28241036, 2017). "Interferon-gamma ELISpot assay was used in HIV uninfected persons with latent and active tuberculosis to map peptide epitopes of Rv2654c." (PMID 26632326, 2016). "Interferon gamma release assays (IGRA) have been developed to support easy and fast diagnosis of diseases like tuberculosis, and CMV in transplant patients." (PMID 25968473, 2015). "The mechanisms of immune protection against human TB are not fully known, however, it is recognized a protective immunity against M. tuberculosis mainly due to the generation of Th1-type cellular response characterized by interferon-gamma (IFN-γ) production." (PMID 24586912, 2014). "Currently, two methods are available for the evaluation of contact with tuberculosis (TB), a tuberculin skin test (TST) and interferon-gamma release assays (IGRAs)." (PMID 25129482, 2014). "Interferon-gamma Release Assays (IGRAs), including QuantiFERON-TB Gold In Tube (Cellestis, Carnegie, Australia) and T-SPOT.TB (Oxford Immunotec, Oxfordshire, UK), are immunological tests that are widely used to detect latent tuberculosis infection (LTBI) in high-income settings." (PMID 25918999, 2014).
tuberculosis (continued). "For the diagnosis of latent tuberculosis infection (LTBI) the tuberculin skin test (TST) has been replaced or supplemented by interferon-gamma (IFN-γ) release assays (IGRA) in many tuberculosis (TB) low-endemic countries due to their simplicity and improved specificity." (PMID 25515915, 2014). "Interferon gamma (IFN-γ) release assays (IGRAs) have added a new dimension to the immune-based diagnosis of TB, as these tests are highly specific and accurate in the diagnosis of Mycobacterium tuberculosis (M.tb) infection, especially when compared to the skin test." (PMID 25025278, 2014). "The screening of tuberculosis in live animals depends on immunological assays such as the single intradermal comparative cervical tuberculin (SICCT) and the interferon-gamma (IFN-γ) tests, which are based on the detection of cell-mediated immune responses." (PMID 25988157, 2014). "Since miR-29a was differentially expressed between children with tuberculosis and LTBI, we compared proportions of IFNγ expressing T cells between these study groups and in children with tuberculosis during treatment and recovery." (PMID 23613882, 2013). "The T-SPOT.TB and QuantiFERON-TB (QFN-TB) assays are commercially available enzyme-linked immunosorbent spot (ELISpot) and enzyme linked immunosorbent assays (ELISAs) that detect IFNγ released by M. tuberculosis antigen-specific cells." (PMID 22778764, 2012). "In a meta analysis of 27 studies evaluating the role of interferon gamma release assays (T-SPOT.TB1, QFT-G-IT), and Tuberculin Skin Test (TST) in diagnosing active tuberculosis, 5 studies used IGRA tests for the diagnosis of pleural TB." (PMID 22474483, 2012). "The Mycobacterium tuberculosis (Mtb)-specific T-cell interferon-gamma release assays (IGRAs) contribute greatly to the diagnosis of tuberculosis (TB), as they are capable of detecting Mtb infection with a higher sensitivity and specificity than the traditional tuberculin skin test (TST)." (PMID 23272100, 2012). "Better characterisation of M. tuberculosis antigen-specific IFNγ responses may improve understanding of the complex immune response in TB and interpretation of IGRAs." (PMID 22778764, 2012). "Interferon gamma (IFN-γ) release assays (IGRAs) are designed to detect both latent Mycobacterium tuberculosis infection (LTBI) and infections manifesting as active tuberculosis disease, collectively referred to as M. tuberculosis infection (MtbI)." (PMID 22970142, 2012). "One could argue that higher IFNγ production should confer a better protection against an intracellular pathogen through macrophage activation, although higher inflammation could also contribute to exacerbated tissue destruction that is required for transmission in tuberculosis." (PMID 22788220, 2012). "IFNγ and IL-10 producing CD4+ T cell clones were first obtained in active tuberculosis patients and patients with Lyme disease." (PMID 23152883, 2012). "The result of an experimental whole blood test based on interferon-gamma (IFNγ) response to RD1-selected peptides, which tends to be related to active tuberculosis, was also positive." (PMID 22233936, 2012). "Clinically, similar findings were noted in reactivating tuberculosis patients on anti-TNF therapy who presented with a decreased T cell activation profile and reduction in IFNγ and IL-10 synthesis." (PMID 22132068, 2011). "The lower rate of IFNγ responses against ESAT-6 by TB cases infected with MAF2 and their exposed contacts may result from defective ESAT-6 secretion, consistent with preliminary results of ESAT-6 immunoblots of culture filtrates of MAF2 and M. tuberculosis." (PMID 20927191, 2010). "While conducting a study of TB diagnostics in a population that had been tested for H. pylori, we fortuitously identified differences in interferon gamma (IFN-γ) and other cytokine responses to M. tuberculosis antigens in H. pylori-infected and uninfected hosts." (PMID 20098711, 2010).
tuberculosis (continued). "This may be attributed to immune modulation of IFNγ responses to specific M. tuberculosis antigens as has been shown in a recent study of household contacts of TB patients." (PMID 19340290, 2009). "We have now extended these studies to analyze the frequency of high and low responder cytokine phenotypes (IFNγ +874 Thi→Alo and IL10 −1082 Glo→Ahi) to analyze the relationship of these SNPs with clinical severity of tuberculosis." (PMID 19274101, 2009). "We have recently reported that the ratio of two key cytokines (IFNγ and IL10) show significant correlation with the severity spectrum of tuberculosis." (PMID 19274101, 2009). "This suggests that although the trend of M. tuberculosis- and BCG-induced IFNγ secretion was similar in TB patients, the responses differed in TST+ and TST- ECs control groups indicating that the immune responses measured here were specific to the mycobacterial stimulus." (PMID 20041183, 2009). "This study investigated the relationship between the interferon-gamma release assay (IGRA) status and pregnancy outcomes in infertile women, with untreated “inactive” tuberculosis lesions observed on chest radiography, who are undergoing in vitro fertilization and embryo transfer (IVF-ET)." (PMID 40776914, 2025). "Interferon gamma release assay (IGRA) testing revealed T-SPOT positivity in 5 patients; among these, 2 had Behçet’s disease and 3 had idiopathic uveitis unrelated to tuberculosis." (PMID 41303213, 2025). "Interferon Gamma Release Assays (IGRAs), such as QuantiFERON-TB (QFT), cannot distinguish latent tuberculosis infection (LTBI) from active tuberculosis (ATB), but they provide a more specific and quantitative assessment of prior exposure to Mycobacterium tuberculosis." (PMID 41471181, 2025). "The most common etiology, tuberculosis-related serpiginous-like choroiditis, was deemed to be unlikely because there was no known exposure to tuberculosis and the interferon gamma release assay bloodwork was negative." (PMID 39554631, 2025). "Some individuals, even when heavily exposed to an infectious tuberculosis patient, do not develop a specific T-cell response as measured by interferon-gamma release assay (IGRA)." (PMID 39747050, 2025). "This was subsequently followed by tuberculosis cultures and interferon-gamma release assays, which were also negative, thus ruling out tuberculosis as a potential cause for the patient’s symptoms." (PMID 41180686, 2025). "Some people who are heavily exposed to an infectious tuberculosis patient do not develop evidence of an antigen-specific T-cell response, as measured with an interferon-gamma release assay (IGRA)." (PMID 39747050, 2025). "An interferon-gamma release assay was performed in this case to rule out tuberculosis, with negative results." (PMID 39135827, 2024). "Patients starting anti-TNF-α therapy were classified as high-risk, and it was recommended to use the tuberculin skin test, interferon-gamma release assay, or both to rule out tuberculosis before beginning the regimen." (PMID 39310504, 2024). "Before initiating immunosuppressive therapy, infectious screening was conducted, including tests for cytomegalovirus (CMV), hepatitis B and C, HIV, and interferon-gamma release assay (IGRA) for tuberculosis (T-SPOT.TB), all of which returned negative." (PMID 39559674, 2024). "Like tuberculosis patients, the CD patients in the TU/ACU study had elevated IFNγ, IL-17 and TNFα." (PMID 38415011, 2024). "This suggests that Mtb infection may have impacted the expression of IL-2 in IFNγ+CD3+ T cells, which could potentially compromise its anti-tuberculosis effector." (PMID 39575242, 2024). "Among the medical institutions, 8.46% were large general hospitals, and the main examinations included chest CT, tuberculosis culture, interferon gamma release assay (IGRA) and tuberculosis antibody detection, PCR technology, bronchoscopy, or other histopathological examinations." (PMID 36927471, 2023).
tuberculosis (continued). "A further possible definition of therapeutic vaccination in the context of tuberculosis is the administration of a vaccine given to people with evidence of M. tuberculosis exposure, e.g. by a positive interferon-gamma release assay (IGRA+ve), to prevent progression to active tuberculosis." (PMID 35812462, 2022). "Prospective studies of interferon-gamma release assays (IGRA) on healthy subjects in tuberculosis-endemic regions have not examined the long-term variability of serial assays." (PMID 35749397, 2022). "Interferon-gamma release assay was positive but tuberculosis DNA qualitative amplification test of sputum was negative." (PMID 35243172, 2022). "The ‘Prevention of tuberculosis in diabetes mellitus’ (PROTID) consortium will randomise 3000 HIV-negative eligible adults with DM and LTBI, as evidenced by a positive tuberculin skin test or interferon gamma release assay, to 12 weeks of 3HP or placebo." (PMID 35689272, 2022). "In migrants who did not develop tuberculosis, males showed greater spontaneous IFNγ production (t = 3.2, P = 0.0013)." (PMID 33796106, 2021). "In line with this, it has been shown that the ratio of IFNγ and IL10 correlates with disease severity of tuberculosis and may differentiate pulmonary from extra-pulmonary forms." (PMID 33767693, 2021). "In addition, IFNG and IL22 gene expression is also increased in tuberculosis LN, but the expression of IL17A was unaffected." (PMID 33057074, 2020). "In a multivariate analysis, a relationship was found between the false positive rate and higher levels of interleukin-6, positive findings on an interferon-gamma release assay for tuberculosis, age < 50 years, and nondiabetic status." (PMID 32764429, 2020). "A study of latent tuberculosis infection (LTBI) burden by chest roentgenography (CXR) with reference to interferon-gamma release assay (IGRA) is still lacking in rheumatic patients of an intermediate tuberculosis burden area." (PMID 32867745, 2020). "Tuberculin skin test and interferon-gamma release assay are not good at differentiating active tuberculosis from latent tuberculosis." (PMID 31388072, 2019). "Interferon gamma (IFN-γ) is a clinically relevant immunomodulatory cytokine that has demonstrated significant potential in the treatment and management of respiratory diseases such as tuberculosis and pulmonary fibrosis." (PMID 30943978, 2019). "For example, it has recently been suggested that H. pylori confers protection against tuberculosis (a lethal disease without appropriate medication) through enhancing IFNγ and Th1-like response to specific tuberculosis antigens." (PMID 28403812, 2017). "Interferon-gamma release assays (IGRAs) and tuberculin skin test (TST), frequently used immunological methods for TB detection, are intrinsically unable to discriminate active tuberculosis (ATB) from latent tuberculosis infection (LTBI)." (PMID 29164066, 2017). "GNLY, granulysin; TB-Ag-stimulated interferon-gamma values, tuberculosis antigen values minus negative-control values in the blood." (PMID 27756230, 2016). "Interferon gamma (IFN-γ) release assays (IGRAs) detect Mycobacterium tuberculosis (Mtb) infection regardless of the active (ATB) or latent (LTBI) forms of tuberculosis (TB)." (PMID 27603919, 2016). "Interferon gamma release assays (IGRAs) do not discriminate between active tuberculosis (TB) and latent TB infection (LTBI), which limit their use in TB endemic areas." (PMID 27685462, 2016). "In consideration of these limitations, this contact investigation conducted screening for tuberculosis using interferon-gamma release assay (IGRA) rather than the TST." (PMID 24454900, 2014). "Immunological tests (i.e. IFNγ release assays and tuberculin skin test) do also not discriminate active tuberculosis and LTBI." (PMID 26567102, 2014).